PEMT (phosphatidylethanolamine N-methyltransferase)
Diseases named in the same sentence as PEMT in open-access papers (continued):
Sharing a sentence is not in itself a finding about the gene and the disease.
dyslipidemia (3 papers, 2023 to 2024). "It will be interesting to determine if the sexually dimorphic dyslipidemia in the Atp10A KO mice is linked to dysregulation of PEMT or to choline deficiency." (PMID 38172157, 2024). "Elevated PEMT expression in vis AT may play a critical role in modulating metabolic pathways, pointing to a profound influence in metabolic syndromes." (PMID 38069170, 2023).
liver cancer (3 papers, 2014 to 2022). An epithelial or non-epithelial malignant neoplasm that arises from the liver. "Studies have shown that the loss of PEMT function as a factor that inhibits the growth and transformation of hepatocytes may lead to an increased incidence of liver cancer." (PMID 36451813, 2022).
squamous cell carcinoma (3 papers, 2014 to 2024). A carcinoma arising from squamous epithelial cells. "Furthermore, in patients with squamous cell carcinoma, PEMT expression in the cancer tissue was equal to that in patients with adenocarcinoma (results not shown)." (PMID 24932311, 2014). "In squamous cell carcinoma (SCC), pEMT is regulated via multiple pathways, including the Hippo (YAP being the effector molecule), Notch, and TGF-β pathways and the microenvironment." (PMID 38444414, 2024).
colorectal cancer (2 papers, 2014 to 2025). A primary or metastatic malignant neoplasm that affects the colon or rectum. "On the one hand, malignant colorectal tumors have an increased PC/PE ratio, which suggests that increased PEMT activity is an essential mechanism for maintaining membrane integrity and to prevent cell death." (PMID 24932311, 2014).
endometriosis (2 papers, 2023 to 2024). The growth of functional endometrial tissue in anatomic sites outside the uterine body. "rs4244593 of PEMT-related polymorphism modulated the choline or phospholipids generation, inducing infertility of endometriosis women.STRA6 is vital for retinol binding protein, and retinol uptake into cells." (PMID 38844959, 2024).
esophageal cancer (2 papers, 2022). A primary or metastatic malignant neoplasm involving the esophagus. "Therefore, it can be further speculated that PEMT enzyme activity may be decreased in esophageal cancer, and abnormal PC metabolism leads to the occurrence of esophageal cancer." (PMID 35782075, 2022). "The correlation of CNV with mRNA expression of choline metabolism-related genes showed that the correlation of PEMT mRNA expression with CNV was positively correlated in 24 of 33 cancers, especially Kidney Chromophobe (KICH), Esophageal carcinoma (ESCA) and Pheochromocytoma and Paraganglioma (PCPG)." (PMID 36451813, 2022).
fibrosis (2 papers, 2018 to 2022). the formation of excess fibrous connective tissue in an organ or tissue in a reparative or reactive process. "As in the overall cohort, we detected lower PEMT expression in postmenopausal women with fibrosis compared to milder NASH stages, although these analyses were limited by the number of individuals in the different NAFLD stages." (PMID 36012560, 2022). "PEMT, AHR, and PC levels are elevated in simple steatosis patients, but PC levels are robustly reduced in steatohepatitis-fibrosis patients." (PMID 29416063, 2018). "Hepatic mRNA levels and protein levels of PEMT and AHR were significantly elevated in both mild simple steatosis and severe NASH-fibrosis patients compared to normal individuals, while SHP mRNA levels were not significantly changed." (PMID 29416063, 2018).
folate deficiency (2 papers, 2015 to 2017). A nutritional condition produced by a deficiency of FOLIC ACID in the diet. "Folate deficiency decreases flux through phosphatidylethanolamine N-methyltransferase (PEMT), an enzyme that synthesizes phosphatidyl-choline (PC) via the methylation of phosphatidylethano-lamine (PE)." (PMID 28783713, 2017). "Furthermore, folate deficiency also reduced PEMT activity and choline kinase expression, and induced the expression of genes involved in hepatic lipid synthesis." (PMID 26337056, 2015).
glioblastoma (2 papers, 2023 to 2025). The most malignant astrocytic tumor (WHO grade IV). "PEMT is also likely the primary source of PC in these tumors through the conversion of PE, and hence its role in the processes of glioblastoma tumorigenesis needs to be explored further." (PMID 37046844, 2023). "Additionally, the conversion of phosphatidylethanolamine to phosphatidylcholine by phosphatidylethanolamine N-methyltransferase is elevated in glioblastoma tumorigenesis." (PMID 40371640, 2025). "Therefore, to better understand glioblastoma, it is necessary to investigate these enzymes, especially PEMT, whose expression is increased in the glioblastoma tumor, and CEPT1, an enzyme that may impact the prognosis for glioblastoma patients." (PMID 37046844, 2023).
lung carcinoma (2 papers, 2014 to 2022). "The Itgav gene codes for an integrin subunit listed among CRC stem cell markers [CD51;], and was recently claimed to induce pEMT in lung cancer synergistically with TGFβ signaling." (PMID 35075245, 2022). "SYBR Green-based real-time polymerase chain reaction was used for quantification of PEMT mRNA in lung cancer tissues." (PMID 24932311, 2014).
non-small cell lung carcinoma (2 papers, 2014 to 2022). A group of at least three distinct histological types of lung cancer, including non-small cell squamous cell carcinoma, adenocarcinoma, and large cell carcinoma. "In the present study, we hypothesized that phosphatidylethanolamine N-methyltransferase (PEMT) gene expression is increased in non-small-cell lung cancer (NSCLC) tissues and that increased gene expression acts as a predictor of shorter patient survival." (PMID 24932311, 2014).
schizophrenia (2 papers, 2024). A major psychotic disorder characterized by abnormalities in the perception or expression of reality. "An example of this is schizophrenia, where the susceptibility to schizophrenia has been linked to the SNP rs464396 in the PEMT gene." (PMID 39409074, 2024). "The PEMT gene that encodes for the enzyme that converts phosphatidylethanolamine to phosphatidylcholine has been linked to development of schizophrenia in Asians due to the identification of three single nucleotide polymorphisms (SNPs) at the PEMT locus." (PMID 38612845, 2024). "However, there are also studies that do not confirm that this polymorphism in the PEMT gene is associated with schizophrenia." (PMID 39409074, 2024).
vitamin B12 deficiency (2 papers, 2011 to 2014). A disease characterized by low serum levels of vitamin B12, either inherited or acquired. "The PEMT mRNA levels in vitamin B12 deficiency in presence of excess folic acid levels (EFBD) were higher (P < 0.01 for all) as compared to control, NFBD, and EFB." (PMID 25003120, 2014). "In the group with vitamin B12 deficiency in the presence of excess folic acid levels (condition for “methyl trap”), there was a reduction of MTHFR and MTR mRNA levels but increase in levels of MAT2a, PEMT, and CBS mRNA levels." (PMID 25003120, 2014).
autism (1 paper, 2024). Persistent deficits in social interaction and communication and interaction as well as a markedly restricted repertoire of activity and interest as well as repetitive patterns of behavior. "When we look at the variant in the PEMT gene (rs7946-T) in our study, four of the autism patients have the homozygous (TT), and three of them have the heterozygous (CT) genotype." (PMID 38807972, 2024). "Considering the variant in the Phosphatidylethanolamine N-methyltransferase (PEMT) gene (rs7946-T), four of the autism patients have the homozygous (TT) genotype, and three have the heterozygous (CT) genotype." (PMID 38807972, 2024).
autism spectrum disorder (1 paper, 2024). A spectrum of developmental disorders that includes autism, and Asperger syndrome. "ASD: Autism Spectrum Disorder; AT: Autoimmune Thyroiditis; MTHFR: Methylenetetrahydrafolatreductase; TCN1: Transcobalamin 1; TCN2: Transcobalamin 2; MTRR: Methionine synthase reductase; PEMT: Phosphoethanolamine N-Methyltransferase." (PMID 38807972, 2024).
diabetic nephropathy (1 paper, 2023). "In addition, PEMT deficiency can suppress ER stress and ameliorate diabetic nephropathy." (PMID 37191416, 2023). "Downregulation of PEMT has also been reported to ameliorate ER stress and reverse apoptosis in diabetic nephropathy." (PMID 37191416, 2023).
gout (1 paper, 2024). A condition characterized by painful swelling of the joints, which is caused by deposition of urate crystals. "Co-localization analysis identified phosphatidylethanolamine N-methyltransferase (PEMT) as a crucial gene associated with gout (pH4 = 0.990)." (PMID 39533594, 2024). "When co-localization analysis was performed using GTEx eQTL data and GWAS data for gout (ukb-b-12765), PEMT was shown to be a gene substantially linked with gout (pH4 = 0.990)." (PMID 39533594, 2024). "Furthermore, we pinpointed PEMT as a crucial gene influencing gout characteristics through co-localization analysis." (PMID 39533594, 2024). "PEMT may serve as a crucial link connecting gout and cancer." (PMID 39533594, 2024).
HCMV infection (1 paper, 2025). "We demonstrate that the activity in the other PC synthesis pathways, the phosphatidylethanolamine N-methyltransferase and Lands cycles, is unaltered by HCMV infection." (PMID 40827916, 2025). "When we tested if HCMV infection altered PEMT activity, we observed a low level of 13C-labeled PC similar to that of uninfected cells." (PMID 40827916, 2025). "Based on the data presented here, we conclude that the increase in the abundance of PC at 72 hpi following HCMV infection occurs independently of the PEMT synthesis pathway." (PMID 40827916, 2025). "Our results indicate that PEMT activity is unaltered by HCMV infection." (PMID 40827916, 2025). "Since PEMT-L may potentially be expressed late, we sought to directly test if HCMV infection alters the activity in the PEMT pathway." (PMID 40827916, 2025). "Additionally, metabolic labeling allowed us to determine that the PEMT pathway that converts PE to PC was not active in HFFs and that HCMV infection does not promote its activation." (PMID 40827916, 2025).
Hepatitis (1 paper, 2025). Inflammation of the liver. "Decreased expression of phosphatidylethanolamine-N-methyltransferase (PEMT) in the liver is reported to promote apoptosis and induce hepatitis." (PMID 40077628, 2025).
Impaired glucose tolerance (1 paper, 2023). An abnormal resistance to glucose, i.e., a reduction in the ability to maintain glucose levels in the blood stream within normal limits following oral or intravenous administration of glucose. "When comparing subjects with impaired glucose tolerance (IGT) or type 2 diabetes (T2D) to those with normal glucose tolerance (NGT), PEMT mRNA expression was significantly higher in vis AT of the former group." (PMID 38069170, 2023).
malaria (1 paper, 2024). Malaria is a serious and sometimes fatal disease caused by a parasite that commonly infects a certain type of mosquito which feeds on humans. "The other major phospholipid in malaria parasite membranes, phosphatidylcholine (PC), can also be produced from ethanolamine by an alternative pathway in the parasite, involving phosphatidylethanolamine N-methyltransferase (PMT)." (PMID 39256807, 2024).
morbid obesity (1 paper, 2023). An excess of body weight, normally defined as an individual with a body mass index greater than 35 or a body weight greater than one hundred percent of ideal body weight. "Furthermore, it should be highlighted that the analyses concerning PEMT mRNA expression in liver and other ATs were based on a cohort of individuals with morbid obesity, all of whom were already diagnosed with NAFLD." (PMID 38069170, 2023).
myocardial hypertrophy (1 paper, 2023). "Therefore, based on previous reports, we can hypothesize that PEMT may be upregulated in myocardial injury, such as myocardial hypertrophy, changing the PC/PE ratio and initiating ER stress, whereas low PEMT levels can alleviate ER stress." (PMID 37191416, 2023).
retinal degeneration (1 paper, 2025). Degeneration of the retina. "Thus, whether TMEM97-associated pEMT promotes or mitigates RPE damage and retinal degeneration remains to be delineated." (PMID 39995975, 2025).
retinoblastoma (1 paper, 2023). A malignant tumor that originates in the nuclear layer of the retina. "Recently, we reported that PRELP regulates cell-cell adhesion of bladder umbrella epithelial cells and retinoblastoma cells through pEMT." (PMID 37936982, 2023).
systemic lupus erythematosus (1 paper, 2022). An autoimmune multi-organ disease typically associated with vasculopathy and autoantibody production. "Studies have shown that the AMPK/PEMT signaling axis is a promising therapeutic target in lipopolysaccharide-tolerant systemic lupus erythematosus mice." (PMID 36451813, 2022).
visceral leishmaniasis (1 paper, 2021). A severe form of leishmaniasis characterized by irregular bouts of fever, substantial weight loss, swelling of the spleen and liver, and anemia (which may be serious). "Miltefosine is a commonly administered oral drug for the treatment of visceral leishmaniasis and CL that targets the PC biosynthetic pathway, inhibiting phosphatidylethanolamine-N-methyltransferase and activating phospholipase A2 in Leishmania." (PMID 34068119, 2021).
tumor (18 papers, 2014 to 2025). "Further analysis identified Basal, Stress, Hypoxia, pEMT, Interferon, and Oxphos signatures in Ep3 cells, classifying them as interferon‐associated basal‐like tumor cells (IFN‐BL tumor cells)." (PMID 40552583, 2025). "This suggests that elevated expression of tumor-intrinsic pEMT genes is associated with NSCLC brain metastasis." (PMID 36216799, 2022). "pEMT drives invasion and metastasis via interactions with CAFs, remodelling the tumour microenvironment and enhancing tumour aggressiveness." (PMID 40318012, 2025). "For example, in hepatocellular carcinomas, PEMT functions as a tumor suppressor, and thus such an agent would lack therapeutic effectiveness." (PMID 39409074, 2024). "This suggests a decrease in PC production through the Kennedy pathway in this tumor, coupled with an increase facilitated by PEMT." (PMID 39409074, 2024). "We also identified another tumor-specific community occupied by pro-tumorigenic states, such as pEMT, epithelial T cell exclusion program, SPP1+ macrophage, and desmoplastic fibroblast." (PMID 38744958, 2024). "While the role of pEMT in tumor initiation has remained elusive, our interrogation of the CSC state now reveals that pEMT represents an early and distinguishing phenotype of CSCs." (PMID 37961717, 2023). "During tumor transformation, cells increase their demand for choline, and heightened PEMT activity might satisfy this demand in specific tumor types." (PMID 39409074, 2024). "Loss of E-cadherin, which might occur through repression by Slug, or its replacement by mesenchymal-type cell adhesion molecules as N-cadherin, play an important role in tumor progression, including the pEMT process and cancer dissemination." (PMID 36289744, 2022). "So, it is believed that the PC metabolic pathway involved in PE may be necessary for tumor growth and development, while the main pathway of PC production is the conversion from PE to PC by the PEMT enzyme." (PMID 35782075, 2022). "In order to study PEMT involvement in tumor growth, we hypothesized that PEMT expression is increased in NSCLC tissue and that increased gene expression acts as a predictor of shorter patient survival." (PMID 24932311, 2014). "The finding that elevated PEMT expression in NSCLC tissue predicts shorter patient survival independently of increased FASN or LPL activities further strengthens the evidence that lipid mobilization is required to sustain tumor growth." (PMID 24932311, 2014). "Indeed, the tumor cores (L and LB) were found to express numerous pEMT genes at significantly greater levels than the TME, including the laminins (LAMC1, LAMC2, LAMA3), integrins (ITGA2, ITGB1, ITGAV), and inflammatory and neutrophil-attracting chemokines (CXCL8, CXCL1)." (PMID 36216799, 2022). "In addition, the functional role of pEMT may vary depending on the type of tumor, the state of spread, and the degree of metastasis and colonization." (PMID 34421348, 2021). "Thus, PEMT may play an important role in tumor growth and progression in addition to lipid mobilization; however, these speculations require further investigation." (PMID 24932311, 2014). "The PEMT gene is not a conventional tumor-suppressor gene; however, several studies have indicated that an increased expression of PEMT is associated with the suppression of hepatocyte growth." (PMID 37191416, 2023). "Based on these studies, while pEMT promotes stemness in SCC, the maintenance of the pEMT phenotype may depend to a large extent on the promotion of tumor cell stemness by some pathways." (PMID 34421348, 2021). "PEMT mRNA was found to inversely correlate with HCC histological stage, and the absence of PEMT mRNA in tumor tissue from cancer patients was associated with poor survival." (PMID 28083512, 2016).